MIR4428 (microRNA 4428)
Synonyms: hsa-mir-4428
Gene: MicroRNA gene on chromosome 1 (237,471,119 to 237,471,191, forward strand). Ensembl gene ENSG00000266262.
Homologues: Orthologues: chimpanzee MIR4428 (100% identical).